ENSG00000262730 (novel transcript)
Gene: Protein-coding gene on chromosome 17 (7,925,931 to 7,930,622, reverse strand). Ensembl gene ENSG00000262730.
Genetic constraint (gnomAD): Missense variants: 6 observed, 7.93 expected, observed/expected ratio (o/e) 0.76, 90% interval 0.41 to 1.47. Synonymous variants: 3 observed, 3.02 expected, observed/expected ratio (o/e) 0.99, 90% interval 0.43 to 1.86.